POMC (proopiomelanocortin)
Diseases named in the same sentence as POMC in open-access papers (continued):
Sharing a sentence is not in itself a finding about the gene and the disease.
Obesity (continued). "In addition, differentiation of these multipotent cells into anorexigenic neurons expressing proopiomelanocortin (POMC neurons) is impaired and, because these neurons control satiety and insulin resistance, their loss upon HFD contributes to the development of obesity and pre-diabetes." (PMID 32185173, 2020). "We hypothesized that maternal HF alters fetal neuroprogenitor cell (NPC) and hypothalamic arcuate nucleus (ARC) development with preferential differentiation of neurons towards orexigenic (NPY/AgRP) versus anorexigenic (POMC) neurons, leading to offspring hyperphagia and obesity." (PMID 33138074, 2020). "However, the genetic link between increased BW, obesity and increased appetite in Labrador and flat coat retrievers has been reported as strongly related to a deletion of the gene POMC via a change in the two peptides β-MSH and β-endorphin that are potent appetite regulators." (PMID 31500653, 2019). "Indeed, impaired POMC processing has been reported to induce obesity in rodents and humans." (PMID 29459251, 2018). "Hence, over-reactivation of the LEPR in hypothalamic neurons, including POMC neurons, may induce obesity in high-fat fed mice." (PMID 29997323, 2018). "Importantly, our Sel1LPOMC mice developed obesity around 15 weeks rather than earlier, as is seen in POMC-deficient mice." (PMID 29457782, 2018). "Our data could suggest that there is potential to exploit the naturally occurring POMC-derived peptides to treat obesity and type-2 diabetes, but this relies on first understanding the specific function(s) for desacetyl-α-MSH and α-MSH in the brain and the periphery." (PMID 29226825, 2018). "Eight-weeks of voluntary exercise has been shown to prevent obesity, hyperphagia, hyperleptinemia and glucose intolerance in young MC4R knockout mice; paradoxically, this effect was associated with increased NPY and decreased POMC and MC3R expression in arcuate nuclei." (PMID 29867590, 2018). "For example, central administration of insulin provokes hyperpolarization of ARC-residing AgRP and POMC neurons, whereas neuron-specific ablation of insulin receptors is associated with diet-induced obesity, and ablation from AgRP, but not POMC neurons, alters hepatic glucose production." (PMID 28121620, 2017). "Thus, to assess whether Ca2+ handling and the function of satiety-mediating POMC neurons are altered in diet-induced obesity, we analyzed the Ca2+-handling properties of these neurons and their intrinsic electrophysiological characteristics in detail." (PMID 28762947, 2017). "On the other hand, mice with a POMC-specific deletion of MFN2 (mitofusin 2), a key protein for mitochondrial fusion and the formation of ER–mitochondria contacts, display a loss of these interactions, defective POMC processing, ER stress-induced leptin resistance, and obesity." (PMID 28270795, 2017). "Given the reported reduction of POMC neuron activity in middle age in mice, these data may have translational relevance by providing a potential molecular explanation for the global sex differences in obesity prevalence." (PMID 26977396, 2016). "Therefore, we speculate that the altered energy expenditure observed during obesity might occur via apelin-dependent mechanisms on POMC neurons since we demonstrate that apelin activates these neurons in the arcuate nucleus." (PMID 27549402, 2016). "Although obesity is most commonly polygenic, rare monogenic forms do exist, and the affected genes described thus far include leptin, the leptin receptor, pro‐opiomelanocortin (POMC), single‐minded 1 (SIM1), neurotrophic tyrosine kinase receptor type‐2 (NTRK2), and the melanocortin 4 receptor." (PMID 26788538, 2016). "Thus, we speculate that the SRC-1-ERα interaction in hypothalamic neurons, including POMC neurons, may be essential for BP control especially in the context of obesity and other metabolic dysfunctions." (PMID 28006821, 2016).
Obesity (continued). "Interestingly, increased glucocorticoids by re-expression of pituitary POMC in neural-specific POMC deficient mice exacerbates obesity with severe insulin resistance, suggesting that central POMC's role is not substituted by peripheral POMC." (PMID 25538630, 2014). "POMC gene deletion in rodents results in significantly reduced metabolic rate, hyperphagia and obesity, primarily from altered lipid metabolism, whereas neuronal overexpression of POMC has been shown to reduce food intake and attenuate obesity in ob/ob mice and obese Zucker rats." (PMID 23924318, 2013). "Interestingly, these mice do not appear to have any defects in weight gain or body composition, though a different strategy aimed at the downregulation of PI3K in POMC neurons does lead to a modest obesity phenotype and increased sensitivity to diet-induced obesity." (PMID 23341784, 2013). "In addition, deletion of LepRs in GABAergic neurons (probably non-NPY/AgRP) produced robust obesity, and this was associated with increased IPSCs onto arcuate POMC neurons." (PMID 23734095, 2013). "Overexpression ↑ diurnal overeating, BW, obesity; associated with elevated circulating leptin and dysfunctional adipocytes with no changes in POMC immunoreactivity; knockdown did not affect basal feeding or weight gain but ↓ fasting-induced hyperphagia and locomotion." (PMID 24385950, 2013). "Our identification of arcuate POMC neurons of DIO mice as being resistant to STAT3 phosphorylation by leptin at least opens the possibility that those specific cells might play a causal role in the development of hyperphagia and diet-induced obesity." (PMID 22276206, 2012). "POMC deficiency could also lead to obesity (due to lack of binding at MC4R), hypocortisolism (due to the lack of binding of ACTH to the MC2R in the adrenal gland), and alteration of pigment (due to lack of binding at MC1R in the skin)." (PMID 22474595, 2012). "POMC is the precursor of hypothalamic neuropeptide, α-melanocyte-stimulating hormone (α-MSH), which is an important hypothalamic regulator of feeding and energy balance, and mutation of POMC gene is sufficient to cause severe obesity and diabetes in both rodents and humans." (PMID 21814490, 2011). "Thus, when challenged with obesity-prone conditions (such as HFD feeding), the susceptibility of disease development is highly increased by HIF dysfunction in hypothalamic POMC neurons, supporting the importance of HIF in the pathogenesis of obesity-diabetes syndrome." (PMID 21814490, 2011). "This stimulates anorexigenic neurons like pro-opiomelanocortin (POMC) and corticotropin—releasing hormone in the arcuate nucleus (ARC) and paraventricular nucleus, suppressing food intake and improving obesity." (PMID 41508004, 2026). "This contrasts with homozygous/bi-allelic carriers of LoF mutations in other genes in the leptin-melanocortin signalling pathway -LEP, LEPR, POMC, PCSK1 and MC4R-who almost inevitably develop severe obesity at an early age." (PMID 41386534, 2026). "People carrying loss-of-function variants in 5-HTR2C, which is primarily expressed on hypothalamic proopiomelanocortin (POMC) neurons, have hyperphagia and weight gain in childhood, leading to severe obesity." (PMID 39926388, 2025). "In line with a role for the leptin-melanocortin system in energy homeostasis, individuals with genetic defects in leptin signaling, POMC, or MC4R present with increased appetite and obesity." (PMID 41251447, 2025). "Activation of hypothalamic GLP-1 receptors enhances satiety signaling by influencing neurons that express pro-opiomelanocortin (POMC) and neuropeptide Y (NPY), mechanisms that reduce excessive food intake and the metabolic load tied to obesity." (PMID 41010364, 2025). "Although deficiency in LepRb Tyr985 caused a lean phenotype despite the occurrence of late-onset obesity, SHP2 deletion in the forebrain promotes early-onset obesity; and its deletion in POMC neurons leads to mild obesity." (PMID 41251447, 2025).
Obesity (continued). "Dysregulation of POMC neuronal activity or impaired sympathetic nervous system (SNS) signaling can lead to metabolic disorders, including obesity and thermogenic dysfunction." (PMID 41040841, 2025). "POMC neurons, located in the ARC of the hypothalamus, play a crucial role in transmitting signals related to body weight and obesity." (PMID 40452923, 2025). "We next examined the effect of mutations in individual genes on image- and biochemistry-based cardiometabolic outcomes, starting with the three autosomal recessive monogenic obesity genes: PCSK1, LEPR, and POMC." (PMID 39948378, 2025). "The “POMC, alpha-MSH, and AGRP in the regulation of food intake and energy expenditure in obesity in the hypothalamus” pathway map (pathway #149; FDR 1.118e-2; 13 modulated network objects out of 43) is highlighted for significant modulation." (PMID 39109301, 2024). "DNA methylation is closely related to the development of obesity by affecting gene expression, then disrupting the regulatory balance between obesity-promoting genes (such as FTO and PPARγ) and anti-obesity genes (such as LEP, GLP-1R, and POMC)." (PMID 39200098, 2024). "Previous studies have suggested that defective regulation of POMC neurons precedes HFD inflammation and obesity development." (PMID 39295865, 2024). "For example, mutations in the genes encoding melanocortin 4 receptor (MC4R), leptin receptor (LEPR), and pro-opiomelanocortin (POMC), result in monogenic obesity." (PMID 38806863, 2024). "Female mice exhibit a greater number and higher activity of anorexigenic proopiomelanocortin (POMC) neurons, which helps limit the development of obesity in females." (PMID 38808032, 2024). "Altogether, these data suggest that PVH neurocircuits are less impacted by HFD-induced obesity in contrast with the effect of HFD on the coordinated interaction between AgRP and POMC neurocircuits." (PMID 38378998, 2024). "Taken together, bidirectional manipulations of neurons of the melanocortin pathway (POMC, AgRP, and MC4R neurons) result in severe obesity as predicted while they fail to achieve the expected obesity prevention and reversal phenotypes." (PMID 37069175, 2023). "Collectively, the reducing effects of HMBA on body weight and food intake were completely abrogated by silencing of Myh9 and Actg1 in AgRP and POMC neurons, suggesting that MYH9 and ACTG1 are required for the anti‐obesity effects of HMBA." (PMID 37984341, 2023). "For instance, deletion of LepRb within microglia diminishes the number of POMC neurons in the ARH, ultimately accelerating in the onset of obesity." (PMID 38027481, 2023). "We found that HMBA bound to MYH9 and ACTG1, which were required for the anti‐obesity effects of HMBA in both NPY‐expressing and POMC‐expressing neurons." (PMID 37984341, 2023). "For example, it has been found in animals that maternal obesity and maternal consumption of HFD in lactation increases hypothalamic expression (mRNA and protein) of NPY and AgRP, whereas reduces POMC expression and decreases sensitivity to leptin." (PMID 37252665, 2023). "A HFD in obesity promotes histone acetylation of genes such as POMC and NPY, which regulate appetite and the dysregulation of which further perpetuates obesity." (PMID 36830032, 2023). "The well-studied monogenic obesity genes BNDF, MC4R, and POMC were only identified by human GWAS, but such genes are likely important BMI factors in both species; for example, knockout mutations in Mc4r produce obesity phenotypes in rats." (PMID 37527041, 2023). "As such, the introduction of omega-3 and omega-9 fatty acids in diet-induced obesity reduced hypothalamic expression of NPY and MCH while increasing expression of POMC and CART in a mouse model." (PMID 37571301, 2023). "Leptin positively regulates these SNS neurons through MBH-localized AgRP/NPY-, POMC/CART-, and SH2B-expressing neurons since deletion of LepR in those neurons results in obesity with the inefficiency of thermogenesis and lipolysis." (PMID 37547309, 2023).
Obesity (continued). "Obesity renders ArcN NPY and POMC neurons resistant to leptin, including those that influence PVN TRH neurons." (PMID 36769012, 2023). "Studies have demonstrated that inhibition of POMC neurons by melanin-concentrating hormone (MCH) through the SIRT1/FoxO1 pathway resulted in hyperphagia and obesity." (PMID 35873818, 2022). "Therefore, olanzapine-induced obesity mediated by POMC may be related to the production of α-MSH." (PMID 35365730, 2022). "POMC (Pro-opiomelanocortin) and NPY (Neuropeptide Y) are two appetite-regulating genes whose methylation is altered in obesity; POMC promotes satiety, while NPY stimulates food intake." (PMID 35163268, 2022). "There is an important role of the primary cilia in the neuronal circuit development of the POMC neurons of the arcuate nucleus of the hypothalamus neurons and they may serve as a critical node that bridges poor early-life nutritional conditions to adult-life obesity and metabolic disorders." (PMID 35207755, 2022). "Inhibition of ciliogenesis in anorexigenic proopiomelanocortin (POMC) hypothalamic neurons, in neonatal mice, leads to adult obesity." (PMID 35902579, 2022). "Obesity is a conspicuous trait of the Ossabaw pig and heterozygosity of POMC, LEP and LEPR genes were reported to impact the obesity of humans and mice." (PMID 34585119, 2021). "The mice targeted restoration of POMC only within 5-HTR2C expressing cells showed sex differences in physical activity, energy expenditure, and the development of obesity." (PMID 34367066, 2021). "Diet-induced obesity increases the intrinsic excitability of ARC N/OFQ neurons, which augments the inhibitory GABAergic tone received by POMC neurons." (PMID 33800452, 2021). "This study suggests that PNE has a potent anti-obesity effect, inhibiting lipogenesis in WAT, even though HFD-induced leptin resistance-mediated disruption of POMC neuronal activity." (PMID 33919440, 2021). "In fact, up-regulation of SOCS3 in proopiomelanocortin (POMC) neurons leads to impairment of STAT3 signaling, with consequential leptin resistance and obesity, as well as glucose intolerance." (PMID 32630697, 2020). "Specifically, genetic disruption of POMC/Pomc and MC4R/Mc4r promotes severe hyperphagia and obesity." (PMID 32166324, 2020). "Here we show that inhibition of ciliogenesis in POMC-expressing developing hypothalamic neurons, by depleting ciliogenic genes IFT88 and KIF3A, leads to adulthood obesity in mice." (PMID 33188191, 2020). "Collectively, these data highlight the role of the ArcN, specifically POMC and NPY neurons, as a site of sexual dimorphism in obesity-induced sympathoexcitation in OP versus OR/control males and females." (PMID 32160920, 2020). "For three types of cancer (LUSC, BLCA, and LUAD), history of smoking and expression levels of three obesity-related genes (SH2B1, POMC, and KCTD15) influenced the survival probability of patients with LUSC." (PMID 33299884, 2020). "The disruption of primary cilia in POMC or AgRP neurons through conditional knockout of ciliogenic genes IFT88 and Kif3a promote hyperphagic induced obesity." (PMID 33139642, 2020). "Compared to the normal tissues, the expression level of each of the three obesity-related genes (LEPR, NEGR1, and POMC) in cancer tissues was found to be insignificant." (PMID 33299884, 2020). "In a study of diet-induced obesity, the genetic ablation of Prkci in proopiomelanocortin (POMC) neurons disrupted leptin action and increased glucose intolerance, insulin resistance and obesity in male mice fed high-fat diets." (PMID 32269838, 2019). "Indeed, inactivation of either α-MSH precursor proopiomelanocortin or of MC4R lead inevitably to hyperphagia, increased preference for fat food, and obesity in genetically modified rodents and may underlie about 2% of genetic causes of obesity in humans." (PMID 30755592, 2019).
Obesity (continued). "The complete prevention of the obesity phenotype of FNΔ2 mice by Vglut2-ires-Cre induction of Pomc expression in hypothalamic neurons did not support our initial hypothesis that a subpopulation of glutamatergic POMC neurons would have selective effects on energy homeostasis." (PMID 30957016, 2019). "Six novel variants were identified in five candidate genes in seven out of 105 children with severe obesity; two in SIM1 (p.W306C and p.Q36X), one in POMC (p.Y160H), one in PCSK1 (p.W130G fs Ter8), two in MC4R (p.D126E) and one in LEPR (p.Q4H)." (PMID 30991789, 2019). "The relevance of NPY and its role, in combination with other regulatory peptides (POMC, AgRP, MC4-R and SOCS3), was clearly seen in adulthood, when obesity was settled in L-females." (PMID 29329236, 2018). "Since hormones like E2 act through PI3K/Akt to diminish EC tone at VMN SF-1/ARC POMC synapses, it stands to reason that decreased ARC PI3K/Akt signaling observed with diet-induced obesity/insulin resistance in males would do just the opposite." (PMID 29973869, 2018). "Consistently, increased SOCS3 expression in POMC neurons results in impaired STAT3 signaling with subsequent leptin resistance and obesity." (PMID 28270795, 2017). "Some of the monogenic obesity genes which manifest as severe obesity in children are leptin (LEP), leptin receptor (LEPR), pro-opiomelanocortin (POMC), and prohormone convertase 1 (PCSK1)." (PMID 28924523, 2017). "In the course of diet-induced obesity (DIO), orexin-A represses satiety-promoting pro-opiomelanocortin (POMC) neurons in the hypothalamic arcuate nucleus (ARC) by eCB-mediated activation of postsynaptic CB1 on POMC neurons." (PMID 28596721, 2017). "Gestational nicotine exposure may not cause obesity and type 2 diabetes in first-generation offspring but instead may moderately enhance central leptin-melanocortinergic regulation of energy and glucose balance via POMC neurons." (PMID 27609221, 2016). "In contrast to the lean phenotype and the resistance to HFD-induced obesity in PIKO mice, inhibition of XBP1 in the hypothalamus results in an obese phenotype in mice, and activation of XBP1 in POMC neurons protects mice against HFD-induced obesity." (PMID 27558934, 2016). "Deletion of SOCS3 in hypothalamic neurons enhances leptin sensitivity, reduces appetite, and protects from diet-induced obesity; while overexpression of SOCS3 in proopiomelanocortin (POMC) neurons leads to hyperphagia and obesity." (PMID 27812350, 2016). "Initially, the coding sequence of three candidate obesity genes, melanocortin-4 receptor (MC4R), agouti-related peptide (AGRP), and POMC, all part of the hypothalamic melanocortin pathway, was examined in 15 obese and 18 lean Labrador retrievers." (PMID 27157046, 2016). "RAI1’s regulation of BDNF in the hypothalamus may contribute to the hyperphagia and obesity seen in Smith–Magenis syndrome and haploinsufficiency of RAI1 results in abnormal expression of a number of genes associated with obesity, including proopiomelanocortin (POMC)." (PMID 24519454, 2015). "On the other hand, insulin and leptin act synergistically on POMC neurons to promote WAT browning and prevent diet-induced obesity." (PMID 26441839, 2015). "The lack of function of β-MSH reduces the amount of MSH peptide in the POMC/MC4R pathway, resulting in obesity." (PMID 25825681, 2015). "Although the 5-HT2CR–POMC axis represents a critical target in the clinical treatment of obesity, recent reports demonstrate that endogenous ARC POMC regulation of energy balance is impaired with aging." (PMID 25051442, 2014). "Increased NPY synthesis and secretion and reduced expression of POMC and its cleaved product α-MSH are characteristic of various models of obesity." (PMID 25258479, 2014). "Insulin administration increases POMC mRNA expression while reducing NPY expression and protecting against diet-induced obesity." (PMID 25258479, 2014).